CBS (cystathionine beta-synthase)
Diseases named in the same sentence as CBS in open-access papers (continued):
Sharing a sentence is not in itself a finding about the gene and the disease.
leukemia (5 papers, 2017 to 2024). A malignant (clonal) hematologic disorder, involving hematopoietic stem cells and characterized by the presence of primitive or atypical myeloid or lymphoid cells in the bone marrow and the blood. "The genes encoding sulfurtransferases and cystathionine beta-synthase could undergo rearrangements and form fusion genes in leukemia cells." (PMID 39062461, 2024). "CBS, essential for hydrogen sulfide production and redox regulation, is crucial in leukemia pathophysiology." (PMID 39062461, 2024). "Our research, identified that CBS expression was higher in various types of leukemia compared to ALL cell lines; with notably lower expression in REH and DND-41 cells (ALL cell lines)." (PMID 39062461, 2024). "A 2005 study on homocysteine junction enzyme expression across various leukemia types established CBS expression levels, noting in the AML HL-60 TB line, CBS was not upregulated, with protein levels closely matching mRNA levels." (PMID 39062461, 2024). "In the present paper, we investigated the expression of TST, MPST, CTH, and CBS in the different types of human leukemia cell lines: B-ALL (REH cells), T-ALL (DND-41 and MOLT-4 cells), AML (MV4-11 and MOLM-14 cells), and CML (K562 cells)." (PMID 35204649, 2022). "In conclusion, our findings showed significant differences in the expression of TST, MPST, CTH, and CBS in different types of human leukemia cells." (PMID 35204649, 2022). "In this study, we examined the expression of three sulfurtransferases and cystathionine beta-synthase in different types of human leukemia cell lines." (PMID 35204649, 2022). "Increased sensitivity to Ara-C was reported to be due to increased expression of the enzyme cystathionine-[β]-synthase (CBS), and to the presence of somatic mutations in the transcription factor gene GATA-1 in leukemia cells of patients with DS-AMKL." (PMID 28143565, 2017). "Increased CBS gene expression in the K562 leukemia cell line affects the activity of various drugs." (PMID 39062461, 2024). "Interestingly, we found significant differences in the mRNA and protein levels of sulfurtransferases and cystathionine beta-synthase in the studied leukemia cells." (PMID 35204649, 2022). "The results of this study can contribute to finding appropriate ways to modulate the activity of sulfurtransferases as well as CBS and the level of sulfane sulfur and H2S in various types of leukemias, thereby regulating oxidative stress and inhibiting the proliferation of these cells." (PMID 35204649, 2022). "CBS is upregulated in many types of cancer and also in leukemia cells." (PMID 35204649, 2022). "Next we treated CML-derived leukemia cell line K562 with the CBS inhibitor." (PMID 33558454, 2021). "Furthermore, reduction of H2S production by inhibition of CBS expression or activity stimulated leukemia cell apoptosis and inhibited cell proliferation by downregulating NF-κB activity." (PMID 33558454, 2021). "Many leukemias, including CML, exhibit higher growth rates in environments with elevated CBS levels." (PMID 39062461, 2024). "It seeks to identify potential bottlenecks in sulfur metabolism in leukemia cells, concentrating on four key enzymes: TST, MPST, CTH, and CBS." (PMID 39062461, 2024). "In different types of leukemia cell lines, such as REH, DND-41, MOLT-4, MV4-11, MOLM-14, and K562, gene expression for TST, MPST, CBS, and CTH was studied on the mRNA and protein level." (PMID 35204649, 2022).
liver disease (5 papers, 2017 to 2022). "Elevated blood methionine concentrations occur not only in CBS deficiency but also in liver disease, methionine adenosyltransferase I/III deficiency and several other inborn errors of metabolism." (PMID 27778219, 2017). "Results from animal models and human liver disease suggest decreased expression of CBS and CSE." (PMID 33807699, 2021). "Although the liver has a remarkable ability to regenerate and recover from injury, the presence of constant pressure in the form of missing CBS activity and additional stressors, such as increased Met intake, likely further exacerbated liver disease and dysfunction in I278T mice." (PMID 32722248, 2020). "With the high expression of the CBS and CSE enzymes in the liver, it is not unexpected to find perturbation of the TSP in human liver diseases." (PMID 33807699, 2021).
pancreatic cancer (5 papers, 2018 to 2026). "Targeting the transsulfuration pathway either by methionine deprivation or pharmacological inhibition of CBS significantly impaired the migration and invasion of metastatic pancreatic cancer cells." (PMID 41923956, 2026). "We validated this finding in pancreatic cancer, where the pathway enzyme cystathionine β-synthase (CBS) and its metabolic products were highly expressed in metastatic cancer cells." (PMID 41923956, 2026). "HSF1 regulates the conversion of homocysteine to cystathionine in the trans-sulfuration pathway by altering levels of cystathionine-β-synthase (CBS), and targeting CBS decreases pancreatic cancer growth while leaving benign prostate cells largely unaffected." (PMID 38172561, 2024). "In cancer-associated fibroblasts, cystathionine beta-synthase (CBS)-dependent transsulfuration pathway supports cysteine synthesis, thereby inducing ferroptosis resistance in pancreatic cancer." (PMID 39624080, 2024). "Moreover, a correlation analysis of CBS and FTH1 showed a significant positive correlation in the controls but a negative correlation in G2 pancreatic tumors." (PMID 34711879, 2021).
thyroid cancer (5 papers, 2019 to 2023). "CBS expression was associated with T classification of thyroid carcinoma." (PMID 35795862, 2022). "In addition, it has been demonstrated that CBS level is increased in thyroid carcinoma compared to benign thyroid tissue, suggesting that CBS may be linked to the development of thyroid cancer." (PMID 35795862, 2022). "Moreover, CBS expression was found to be associated with T classification of thyroid carcinoma." (PMID 35795862, 2022). "Nevertheless, the mechanism of action of CBS in the growth of human thyroid cancer remains unrevealed." (PMID 35795862, 2022). "CBS can regulate the proliferation, migration, and invasion of human thyroid cancer cells via ROS-mediated PI3K/AKT/mTOR and Wnt/β-catenin pathways." (PMID 35795862, 2022). "In the current study, we determined the mechanism of action of CBS in the proliferation, migration, invasion, and cell cycle progression of human thyroid cancer and investigated the effect of CBS on the growth of xenografted thyroid carcinoma." (PMID 35795862, 2022). "The overexpression of CBS enhanced the proliferation, migration, and invasion of thyroid cancer cells, while the downregulation of CBS exerted reverse effects." (PMID 35795862, 2022). "The protein expressions of CBS were dramatically increased in all human thyroid cancer cell lines compared with normal thyroid cell line." (PMID 35795862, 2022). "The data indicated that CBS expression was higher in each clinical stage of human thyroid carcinoma compared with adjacent tissues." (PMID 35795862, 2022). "CBS overexpression significantly enhanced the growth of thyroid carcinoma xenograft tumors, while CBS knockdown dramatically decreased tumor growth." (PMID 35795862, 2022). "Our data suggested that CBS overexpression decreased the ROS levels, and CBS knockdown promoted ROS generation in human thyroid carcinoma cells." (PMID 35795862, 2022). "Novel donors that inhibit the expression of CBS can be developed in the treatment of thyroid carcinoma." (PMID 35795862, 2022). "In sum, the results suggest that CBS can regulate the growth of xenografted human thyroid carcinoma." (PMID 35795862, 2022). "We found that CBS can mediate the cell cycle, proliferation, migration, and invasion of human thyroid carcinoma cells via ROS-mediated PI3K/AKT/mTOR and Wnt/β-Catenin signaling pathways." (PMID 35795862, 2022). "The results show that CBS can modulate mitochondria-dependent apoptosis in human thyroid carcinoma cells." (PMID 35795862, 2022). "The data suggest that CBS can be a potential marker for the diagnosis and prognosis of thyroid carcinoma." (PMID 35795862, 2022). "Collectively, these results indicate that CBS is involved in the regulation of the growth, migration, invasion, and cell cycle of human thyroid carcinoma cells." (PMID 35795862, 2022). "And yet, the mechanism of action of CBS in the growth of thyroid carcinoma cells is still unrevealed." (PMID 35795862, 2022). "The role of aminooxyacetic acid (AOAA, an inhibitor of CBS) in thyroid carcinoma cell growth was further detected." (PMID 35795862, 2022). "Adrenocortical cells express CBS in adrenal glands, while CBS expression in thyroid gland is low but markedly increases in thyroid carcinoma (see also below)." (PMID 32365821, 2020). "In addition, in various types of thyroid cancer, the expression of CBS is up‐regulated to varying degrees, and the highly expressed CSE can also activate the hedgehog signalling pathway to promote the occurrence and development of thyroid papillary carcinoma." (PMID 36929586, 2023). "In addition, the content of CBS in the thyroid is low and it is significantly increased in thyroid cancer." (PMID 36929586, 2023). "Furthermore, a recent study has shown that the expression level of CBS in thyroid carcinoma is higher than that in benign thyroid." (PMID 35795862, 2022).
thyroid cancer (continued). "Furthermore, CBS overexpression significantly enhanced the levels of H2S in human thyroid carcinoma cells and supernatant, whereas CBS knockdown exhibited reverse trends." (PMID 35795862, 2022). "Furthermore, aminooxyacetic acid (an inhibitor of CBS) dose-dependently inhibited thyroid carcinoma cell growth." (PMID 35795862, 2022). "Furthermore, CBS expression level in human thyroid carcinoma was detected using a tissue chip that consists of 54 thyroid carcinoma samples and surrounding tissues using IHC." (PMID 35795862, 2022). "The results together conclude that CBS can regulate cell cycle in human thyroid carcinoma cells." (PMID 35795862, 2022). "We firstly determined the level of CBS in human thyroid carcinoma cell lines." (PMID 35795862, 2022). "Nevertheless, the effect and mechanism of CBS on the growth of human thyroid carcinoma cells remain unknown." (PMID 35795862, 2022). "Taken together, CBS could regulate the growth of human thyroid carcinoma xenograft tumors through the mediation of angiogenesis, cell cycle, and apoptosis." (PMID 35795862, 2022). "Considering its role in the progression of human thyroid carcinoma cells, CBS may act as a promising biomarker for the diagnosis and prognosis in thyroid carcinoma patients." (PMID 35795862, 2022). "We found that CBS level in thyroid carcinoma tissue was higher than that in adjacent normal tissue." (PMID 35795862, 2022). "In addition, CBS overexpression promoted the growth of xenografted thyroid carcinoma, whereas CBS knockdown decreased the tumor growth by modulating angiogenesis, cell cycle, and apoptosis." (PMID 35795862, 2022). "Knockout or knockdown experiments could be performed to clarify the mechanism of action of CBS in the procession of thyroid carcinoma." (PMID 31223424, 2019). "Whether CBS-derived H2S could mediate the growth of human thyroid carcinoma cells needs to be further investigated." (PMID 31223424, 2019). "According to these findings, it can be concluded that CBS level is high in thyroid cancer tissues and low in adjacent nontumor tissues, indicating that CBS is an important biomarker for the diagnosis and prognosis of thyroid cancer and can play a role in the development of thyroid cancer." (PMID 35795862, 2022). "In addition, CBS could be a novel therapeutic target and novel donors that inhibit the expression of CBS can be developed in the treatment of thyroid carcinoma." (PMID 35795862, 2022). "Thus, CBS can modulate mitochondria-dependent apoptosis in human thyroid carcinoma cells." (PMID 35795862, 2022). "In addition, 25–50 μM NaHS increased the expression levels of CBS, while 200 μM NaHS exerted reverse effects, suggesting that CBS may mediate the effects of H2S on the growth of human thyroid carcinoma cells." (PMID 31223424, 2019). "CBS overexpression reduced the levels of cleaved caspase-3 and cleaved poly ADP-ribose polymerase in thyroid cancer cells, whereas CBS knockdown showed reverse trends." (PMID 35795862, 2022). "Our data together indicate that CBS modulates ROS-mediated PI3K/AKT/mTOR and Wnt/β-Catenin pathways in human thyroid carcinoma cells." (PMID 35795862, 2022). "Overall, these data suggest that CBS modulates ROS-mediated PI3K/AKT/mTOR and Wnt/β-Catenin pathways in human thyroid carcinoma cells." (PMID 35795862, 2022). "The reasons for the differences in CBS and CSE expression in thyroid cancer shown in these studies likely lie in the different patient populations analyzed and the different experimental techniques used." (PMID 35366284, 2021). "Administration of 50 μM NaHS increased the expression levels of CBS, SQR, and TST, while 200 μM NaHS showed reverse effects in human thyroid carcinoma cells." (PMID 31223424, 2019). "We further determined the protein levels of CBS in fresh tissues of thyroid cancer and their surrounding nontumor tissues." (PMID 35795862, 2022).
thyroid cancer (continued). "In conclusion, our results demonstrate that the expression level of CBS in human thyroid carcinoma tissues is higher than that in adjacent nontumor tissues." (PMID 35795862, 2022). "In line with the previous study, our results indicated that CBS level was higher in thyroid carcinoma tissues than that in adjacent nontumor tissues." (PMID 35795862, 2022). "The data together suggest that CBS inhibitor could suppress human thyroid carcinoma cell growth without significant toxicity." (PMID 35795862, 2022).
vitamin B12 deficiency (5 papers, 2014 to 2024). A disease characterized by low serum levels of vitamin B12, either inherited or acquired. "However, excess folic acid with a vitamin B12 deficiency (EFBD) resulted in higher (P < 0.01 for all) CBS mRNA levels as compared to the control, NFBD, and EFB groups." (PMID 25003120, 2014). "In vitamin B12 deficiency, methionine block implies that SAM (driven by Met) is lowered as well and hence it is plausible CBS is less effective." (PMID 27047940, 2016). "Overall, 166 newborns (prevalence 1: 3305) were confirmed (positive predictive value: 0.36); specifically, methylmalonic acidurias (N = 5), propionic acidemia (N = 4), remethylation disorders (N = 4), cystathionine beta-synthase (CBS) deficiency (N = 1) and neonatal vitamin B12 deficiency (N = 153)." (PMID 37571294, 2023). "In the group with vitamin B12 deficiency in the presence of excess folic acid levels (condition for “methyl trap”), there was a reduction of MTHFR and MTR mRNA levels but increase in levels of MAT2a, PEMT, and CBS mRNA levels." (PMID 25003120, 2014).
Cirrhosis (4 papers, 2019 to 2025). A chronic disorder of the liver in which liver tissue becomes scarred and is partially replaced by regenerative nodules and fibrotic tissue resulting in loss of liver function. "Furthermore, the liver tissues of patients with liver failure and hepatic cirrhosis exhibited downregulated expression of CBS, CYP1A2, FOXA1, GSTZ1, WDR72 and UHMK1 when compared to healthy controls." (PMID 38287425, 2024).
clear cell renal cell carcinoma (4 papers, 2013 to 2025). "However, decreased CBS expression was determined in clear cell renal cell carcinoma that was spontaneously hypoxic compared to the matched controls, and this decrease was dependent on the grade of tumor." (PMID 37483514, 2023). "Moreover, levels of CBS were decreased by the higher grade of clear cell renal cell carcinoma." (PMID 37483514, 2023).
dementia (4 papers, 2016 to 2022). Loss of intellectual abilities interfering with an individual's social and occupational functions. "The results suggest a reduced activity of cystathionine β-synthase activity (CBS) in AD and PD with dementia, in the latter case, seemingly accompanied by reduced re-methylation flow via MTR not attributable to folate status." (PMID 35276958, 2022). "We found changes in one-carbon metabolites that indicate inefficient activation of cystathionine β-synthase (CBS) in AD and PD subjects with dementia, the latter seemingly accompanied by a restricted re-methylation flow." (PMID 35276958, 2022). "In conclusion, the intensity and distribution of binding of the tau ligand [18F]AV‐1451 in a patient with a MAPT 10 + 16C>T mutation supports the use of this ligand in clinical studies of dementia, including frontotemporal lobar degeneration and CBS." (PMID 28097206, 2016). "Its physiological levels are now considered neuroprotective, and its reduction in response to inefficient CBS pathway in AD and PD dementia is pro-inflammatory and may exacerbate the pathology." (PMID 35276958, 2022). "This is consistent with the trend (albeit non-significant) toward lower Hcy in both groups with non-demented DOPA+ PD subjects, as an expected after-effect upon activation of CBS and rapid clearance of Hcy, as opposed to its accumulation in PD subjects with dementia." (PMID 35276958, 2022).